WEE1 (WEE1 G2 checkpoint kinase)
Diseases named in the same sentence as WEE1 in open-access papers (continued):
Sharing a sentence is not in itself a finding about the gene and the disease.
tumor (continued). "Various anti-tumor drugs, including conventional chemotherapy agents like 5-fluorouracil, docetaxel, and paclitaxel, as well as novel targeted therapies such as lapatinib, trametinib, and Wee1 inhibitor, have demonstrated therapeutic efficacy against various malignancies, including CRC and CRLM." (PMID 40892354, 2025). "In addition, the phosphorylation of key molecular CDC2 involved in the G2/M checkpoint was downregulated upon the knockdown of E-cadherin, which can enhance the anti-tumor activity of the Wee1 inhibitor AZD1775 by impairing the G2/M checkpoint and promoting premature mitosis." (PMID 39349771, 2024). "Moreover, the expression of programmed cell death ligand 1 (PD-L1) was increased, while Ki67 expression was significantly decreased in the treatment group compared to that in the control group, suggesting that the WEE1 inhibitor suppressed tumor cell proliferation." (PMID 39335109, 2024). "Notably, the combined inhibition of KRAS-G12C and WEE1 consistently suppresses tumor growth." (PMID 38776912, 2024). "Therefore, blocking either HDAC and/or tyrosine kinase cell-cycle progression regulator WEE1 may represent therapeutic vulnerabilities in these tumors, potentially restoring their tumor immunogenicity." (PMID 38036539, 2023). "However, there are conflicting views on the mechanisms by which Wee1 regulates tumor resistance." (PMID 37102239, 2023). "Moreover, tumor cells with loss of H3K36me3 due to mutation in SETD2, the gene that encodes a histone lysine methyltransferase, or mutation in histone H3 itself showed HR, NHEJ, and MMR impairment and sensitivity to WEE1, CHK, or ATR inhibitors." (PMID 36499000, 2022). "This indicates that WEE1 may be a good candidate target for tumor therapy." (PMID 35127343, 2022). "However, in both mouse and human SCLC models (treatment naive or relapsed), the evaluation whether there is benefit from combining WEE1 inhibition with chemoimmunotherapy on tumor growth and on related to immune subsets will be a focus of future work." (PMID 35584676, 2022). "Importantly, several preclinical studies in mice also showed increased tumor delay when radiation was combined with Wee1 inhibition and several clinical trials are currently examining the efficacy of AZD1775 with radiation therapy (sometimes in combination with chemotherapy)." (PMID 35251998, 2022). "Importantly, silencing of FOXM1 and WEE1 also impaired subcutaneous tumor formation by STS cells." (PMID 33564073, 2021). "Moreover, an in vitro study has pointed out that WEE1 inhibition selectively kills tumor cells, so WEE1 inhibitors may have a role as targeted therapy for CRC." (PMID 34201502, 2021). "Finally, we assessed in vivo the potency of BCL‐XL+WEE1 co‐targeting on tumor growth." (PMID 33552868, 2021). "Thus, increased Wee1 expression may represent an adaptive response to the chemotherapy that allows tumor cells to repair DNA damage and thereby survive." (PMID 34639030, 2021). "Furthermore, statistic analysis indicated that the expression of WEE1 protein was associated with T stage, lymph node metastasis and stage, but not with age, tumor grades and tumor primary locations." (PMID 30323762, 2018).
tumor (continued). "Collectively, these data suggest that miR-497 may regulate proliferation, survival and tumor vascular permeability by targeting key genes involved in DDR such as WEE1 and CHEK1, cell growth and viability such as AKT3 and BCL2 and angiogenesis regulators such as VEGFA." (PMID 26824183, 2016). "Future studies investigating its requirement in IR-induced or replication stalling induced WEE1 checkpoint functions may reveal whether anti-tumor activity of WEE1 inhibitors is a combination of suppression of WEE1 epigenetic activity and blockade of cell cycle progression." (PMID 26546517, 2015). "Our data suggest that WEE1 overexpression may be essential for tumour cell viability." (PMID 19357772, 2009). "Typical examples include combining the PARPi olaparib with the anti‐angiogenic antibody bevacizumab to enhance tumour sensitivity to PARP inhibition, and pairing PARPis with agents targeting other SL‐related genes, such as WEE1, ATR or CHK1 inhibitors." (PMID 41537447, 2026). "To increase clinical relevance we analyzed published results of clinical trials and reported blood tumor barrier (BTB) penetration of the WEE1 inhibitor adavosertib and the ATM/ATR inhibitor BAY-1895344." (PMID 41585496, 2026). "WEE1 inhibits CDK1 activity, leading to cell cycle arrest and preventing apoptosis, thus supporting tumor growth and survival." (PMID 39820427, 2025). "Therapies targeting G2/M checkpoint proteins (e.g., CDK1, Wee1, CHK1/CHK2) are being actively explored to control tumor growth and improve treatment outcomes." (PMID 40894036, 2025). "More broadly, small-molecule inhibitors of PARP, WEE1, and HDAC have been shown to sensitize tumor cells to avelumab-mediated ADCC." (PMID 41417226, 2025). "To investigate the anti-tumor mechanisms of AZD1775, we examined the protein expression levels of p-WEE1 (Ser642), p-CDK1 (Tyr15), and p-γH2AX (Ser139) in PDX tumor lysates using Western blot." (PMID 40551232, 2025). "Bedsides, in BRCA1/2 wild-type TNBC models, combined inhibition of WEE1 and PARP (Olaparib) markedly suppresses tumor growth and reshapes the tumor microenvironment." (PMID 40949156, 2025). "The highest cytotoxicity and tumor growth suppression to AZD1775 therapy were observed in PDXOs and PDXs with high WEE1 expression." (PMID 40551232, 2025). "WEE1, a cell cycle regulator in the G2/M and S phases, was predominantly detected in the nuclei of tumor cells within PDX#1, #2, and #3 tumor tissues and was highly expressed in PDX#3 tumor tissue compared to the other tumor tissues." (PMID 40551232, 2025). "Inhibition of WEE1 exerts antitumor effects against CRC by stimulating cell cycle progression, inducing apoptosis, enhancing tumor immunity, and suppressing the stromal response." (PMID 39335109, 2024). "WEE1 inhibitors have been reported to activate the cytosolic-DNA sensing, interferon, and JAK-STAT pathways, thereby enhancing tumor immunity through CD8+ T cell infiltration, increased cytokine and chemokine signaling, and increased PD-L1 expression." (PMID 39335109, 2024). "Our previous data showed that SHCBP1 knockdown led to early M-phase entry by downregulating WEE1 expression and subsequently reducing CDK1 phosphorylation at Tyr15, resulting in the abrogation of the G2–M checkpoint in tumour cells." (PMID 38365687, 2024). "The combination of a WEE1 inhibitor and a PARP inhibitor exhibits promising antitumor efficacy within circulating tumor cell (CTC)-derived explant SCLC models." (PMID 39103941, 2024). "Their experiments using NEPC transgenic mouse models demonstrated that treatment with the Wee1 inhibitor AZD1775 and CHK1 inhibitor SRA737 effectively inhibited tumor growth, providing a promising approach for NEPC treatment." (PMID 39204153, 2024).
tumor (continued). "The radiosensitising potential of Wee1 inhibition, in addition to cell lines, has also been shown in xenograft and PDX in vivo models through decreases in tumour growth and increased overall survival of the mice." (PMID 39272874, 2024). "We demonstrated elevated WEE1 expression and potent cell-killing effects of AZD1775 in NEPC cells and tumor spheroids, which is consistent with the evidence that WEE1 was previously identified as a potential target for NEPC tumors." (PMID 37987002, 2023). "This patient’s tumor organoids also showed an exceptional response to the investigational BET inhibitor CPI-0610 and a good response to the WEE1 inhibitor adavosertib, suggesting additional targetable vulnerabilities." (PMID 37202426, 2023). "The expression of WEE1 and CHK1 was also elevated in NCI-H660 (H660), an authentic NEPC cell line derived from a clinical NEPC patient tumor." (PMID 37987002, 2023). "Nonetheless, combined PARP and WEE1 inhibitor treatment was shown to promote anti-tumour immunity in the AT3 and AT3OVA tumour microenvironment, potentially rendering the tumours more sensitive to immunotherapy." (PMID 37582853, 2023). "It is suggested that the combination of a WEE1 inhibitor and an ATR/ATM inhibitor can enhance the anti-tumor efficacy in insensitive tumor cells." (PMID 37305685, 2023). "Consistent with the anti-tumour effect of combined PARP and WEE1 inhibitors being dependent on T cells, the anti-tumour immune response to olaparib and AZD1775 treatment was not as pronounced in the AT3 compared with the AT3OVA tumours." (PMID 37582853, 2023). "WEE1 is a mitotic protein kinase able to produce G2 phase arrest through CDK1 phosphorylation and, as a consequence, allows DNA reparation in tumour cells." (PMID 37514027, 2023). "Co-inhibition of WEE1 and ATM can reduce the expression of cytokines such as MMP-9 and IL-8, which are closely related to the migration and invasion abilities of tumor cells." (PMID 37305685, 2023). "Worthy of note is that we also found over-expression of WEE1, of which multiple inhibitors have entered clinical trials, in 4/4 PFA and 3/4 RELA tumor sets." (PMID 36335125, 2022). "Wee1 inhibition by AZD1775 has been shown to induce in vitro and in vivo synergistic tumor cell killing with several DNA damaging therapies including IR and chemotherapeutics like cisplatin, paclitaxel doxorubicin, 5-fluorouracil, and gemcitabine." (PMID 35251998, 2022). "The co-administration of Olaparib and AZD1775 (WEE1 inhibitor) demonstrated a synergistic antiproliferative effect in TNBC cell lines and significantly inhibited tumor growth in a xenograft model of BC." (PMID 36499000, 2022). "The inhibition of WEE1 activity increased the radiosensitivity of DIPG cells in vitro, reduced tumor burden in vivo, and prolonged the survival of orthotopic mice." (PMID 35158967, 2022). "Pharmacologic inhibition of WEE1 induces apoptosis in CIC–DUX4 cells, thus identifying WEE1 as a vulnerability targetable in this tumor type." (PMID 36358827, 2022). "Inhibition of WEE1 impairs RS response activated by ATR, and thus increasing tumor cell radiosensitivity." (PMID 35875060, 2022). "The evidence suggests that WEE1 inhibition impairs the RS response activated by ATR, and thus increases tumor cell radiosensitivity." (PMID 35875060, 2022). "Inhibition of WEE1 radiosensitized HGG cells, when applied 24 h after the RT, decreased tumor burden and increased survival in RT-treated animals." (PMID 35158967, 2022). "The WEE1 inhibitor PD0166285 in combination with RT reduced the viability of GBM cells, reduced tumor burden, and prolonged animal survival." (PMID 35158967, 2022).
tumor (continued). "WEE1 and CHK1 play a pivotal role in DNA damage response (DDR) activated in the CSC populations from different tumor entities." (PMID 34079088, 2021). "Further signaling network analysis highlights potential druggable targets, of which cotargeting of WEE1 and BCL‐XL synergistically kills TNBC cells and efficiently induces tumor regression." (PMID 33552868, 2021). "Expression of WEE1 (P = .006), CDK6 (P = .02), and CDK7 (P < .001) was enriched in the squamous subtype in both PDCLs and bulk tumor." (PMID 33039466, 2021). "Previously, tumor cells with genome instability due to defective homologous recombination were shown to depend on the ATR and WEE1 replication checkpoint kinases for their survival." (PMID 33028815, 2020). "Several targeted compounds showed an inhibitory activity on WEE1 and PKMYT1 kinases and their efficacy was proven in a number of tumor types." (PMID 32958072, 2020). "In this study, both WEE1 and BRCA1 were found to be up‐regulated by enhanced TFAP2C mRNA stability and they drove tumour growth in vivo." (PMID 32857912, 2020). "In another combination study, while EMT6 model was largely resistant to AZD-1775, a WEE1 inhibitor currently in phase 2 clinical development, addition of DN052 drastically enhanced tumor growth inhibition compared to either agent alone." (PMID 35006413, 2020). "The top five lethal siRNAs in VU-preSCC-M3 were directed against KIF11, RRM1, NHP2L1, WEE1 and SF3B1, and all showed effect in at least 9 of 12 tumor cell lines." (PMID 32047167, 2020). "We then modeled the combination of platinum-based chemotherapy and trientine, Wee1 inhibitor, or birinapant as examples of drugs targeting the different resistance mechanisms and estimated their effects on PFI and tumor composition." (PMID 31822719, 2019). "Oncogene-induced replication stress serves as a tumour specific vulnerability and rationale for the clinical development of inhibitors targeting the DNA damage response (DDR) kinases (CHK1, ATR, ATM and WEE1)." (PMID 31500184, 2019). "The biggest decrease in tumor burden (99.99%) and improvement in PFI (19 months, p < 0.00001, log-rank test) was obtained when Wee1 inhibitor was combined with platinum." (PMID 31822719, 2019). "Since DLBCL is a tumor with high levels of DNA damage, targeting proteins involved in DDR and damage repair, such as WEE1 and PARP1, is a rational choice for therapy in DLBCL." (PMID 29489886, 2018). "Here, we have investigated the expression and clinical significance of WEE1 in LSCC, and the anti-tumor effects and mechanisms of WEE1 inhibition against LSCC." (PMID 30323762, 2018). "Several important cell cycle regulators were found differentially expressed in the reprogrammed tumours, including CDK4, E2F5, and CDKN1B (P27), WEE1, CDKN3." (PMID 29662623, 2018). "Mechanistically, MLN4924 blocked the neddylation of cullins and induced accumulation of several tumor-suppressive substrates of Cullin-RING E3 ubiquitin ligases (CRLs), including CDT1, Wee1, p21, p27, Noxa, and p16." (PMID 27223074, 2016). "WEE1 and PLK1 are involved in the G2/M phase of cell cycle regulation, and TAK1 is an upstream activator of the tumor-promoting NF-kB signaling." (PMID 27558154, 2016). "The RT-qPCR data demonstrated that WEE1 mRNA is over-expressed in both GBMs and TIC lines compared to non-tumor controls." (PMID 21358821, 2011). "Our results demonstrated that WEE1 inhibitor at lower concentrations did not significantly inhibit tumor growth on its own, but significantly enhanced the inhibitory effects of the G12C inhibitor." (PMID 40885709, 2025). "CRISPR-mediated CCNE1 perturbation and patient-derived endometrial xenograft models could clarify the effects of CCNE1 on tumor growth, immune infiltration, and sensitivity to CDK2 or WEE1 inhibitors." (PMID 41331376, 2025).
tumor (continued). "The combination of WEE1 and CHK1 inhibitors demonstrated a synergistic inhibitory effect on the growth of B and T cell precursor acute lymphoblastic leukaemia (B/T-ALL) tumors and induced tumor cells to enter apoptosis." (PMID 40240755, 2025). "Since tumor cells are under constant oncogenic stress, they become addicted to checkpoint signals arising from kinases such as ATR (Ataxia Telangiectasia and Rad3-related protein), Chk1 (checkpoint kinase 1) and Wee1." (PMID 40628724, 2025). "Previous studies have revealed that the combination of cisplatin, with Wee1 and PARP inhibitors could significantly augment anti-tumor activity compared to mono-therapy." (PMID 39349771, 2024). "Inhibition of WEE1 promotes the immune response via the STING-TBK1-IRF3 pathway, enhances the antitumor effect of PD-L1 antibodies through the STAT1 pathway, and significantly suppresses tumor progression in SCLC models (including MYC-stabilized SCLC)." (PMID 39103941, 2024). "Preclinical studies identified CIC::DUX4 to molecularly depend on cell cycle mediators CCNE1 and WEE1 with CCNE1 being established as a direct transcriptional target of CIC::DUX4 that drives tumor growth and survival through an acquired dependence on CCNE/CDK2 complex." (PMID 38882060, 2024). "Moreover, eIF3a expression was found to be related to chemosensitivity of several anti-tumor drugs in DLBCL, including Vincristine and Wee1 inhibitor." (PMID 38589831, 2024). "A second predicted damaging variant at chr21:32854760, V468A within the kinase domain of WEE1, was identified in another tumor however evidence from RNAseq was not sufficient to rule out error and further sequencing is required to confirm." (PMID 38778091, 2024). "Concurrently, in vivo analyses revealed that WEE1 inhibitors robustly hampered tumor occurrence and progression, without detrimental impacts on the growth parameters of the host mice, such as body weight." (PMID 38169513, 2024). "We sought to determine whether PD-1 blockade would potentiate the anti-tumour activity of combined PARP and WEE1 inhibition." (PMID 37582853, 2023). "Moreover, much research has verified the overexpression of DNA damage repair (DDR) proteins, such as Wee1, in SCLC tumor tissues compared to paracancerous." (PMID 37102239, 2023). "In contrast, the AZD1775 IC50 increased by approximately 4.5-fold in the tumor cells isolated from the AZD1775-treated cells compared with the treatment-naive tumor cells, indicating the successful induction of resistance to WEE1 induction in vivo." (PMID 36378528, 2023). "Whereas depletion of either CD8+ or CD4+ T cells alone did not affect treatment efficacy of olaparib and AZD1775 suggesting that the cytotoxicity of both CD8+ and CD4+ T cells is essential for the anti-tumour efficacy of combined PARP and WEE1 inhibition in the BRCA1/2 wild-type AT3OVA TNBC model." (PMID 37582853, 2023). "Combined inhibition of WEE1 and CHK1 blocked NEPC tumor progression and metastasis." (PMID 37987002, 2023). "Importantly, organoid cultures EOC989 and EOC884, which were derived from residual tumour cells from patients treated with chemotherapy (NACT), showed prominent synergistic response to the combined WEE1 and PKMYT1 inhibition." (PMID 37325550, 2023). "In addition, the co-inhibition of WEE1 and ATM inhibited the activation of the FAK-Src-CREB signaling pathway, which is closely related to the migratory invasive ability of tumor cells." (PMID 37305685, 2023). "It was therefore of relevance to determine if and how differences in quantity of pre-existing TILs might affect the anti-tumour efficacy and immune response of combined PARP and WEE1 inhibition in the BRCA1/2 wild-type TNBC models." (PMID 37582853, 2023).